MOAP1 (modulator of apoptosis 1)
Diseases named in the same sentence as MOAP1 in open-access papers (continued):
Sharing a sentence is not in itself a finding about the gene and the disease.
cancer (continued). "In this study, we present several lines of evidence from cancer databases, immunoblotting of cancer cells, proliferation, and xenograft assays as well as DNA microarray analysis to demonstrate the role of MOAP-1 as a tumor suppressor protein." (PMID 26269600, 2015). "Together, these results demonstrate tumor suppressor properties of MOAP1 via repressing cell proliferation and promoting cell death in cancer cell lines." (PMID 26269600, 2015). "Preliminary evidence does suggest that there is a strong positive correlation between RASSF1A and MOAP-1 expression in cancer cells." (PMID 26269600, 2015). "Quantitative PCR revealed decreased mRNA production for MOAP-1 in several cancer cells and patient tumor tissues." (PMID 26269600, 2015). "This would suggest that ubiquitin-directed modulation of MOAP-1 expression can occur in several cancers." (PMID 26269600, 2015). "In summary, MOAP1 plays a critical role in the development and progression of cancers and neurological diseases by regulating a few genes related to cellular apoptosis such as BAX and RASSF1A and interacting with disease-associated miRNAs, including miR-25 and miR1228." (PMID 35269511, 2022). "Also, strategies that lead to enhanced expression and stabilization of MOAP-1 protein in cancer cells are likely to confer tangible benefits for therapeutic intervention in cancer." (PMID 35082905, 2022). "MOAP1 was involved in cancer drug resistance and chemo-sensitization." (PMID 35269511, 2022). "Taken together our data thus suggest that the apoptosis signaling mediated by α-mangostin in human cancer cells that involves the activation of MOAP-1 and BAX is likely to impact on other signaling pathways activated by α-mangostin, such as cell cycle arrest, leading to apoptotic cell death." (PMID 35082905, 2022). "We explored the mRNA expression of both RASSF1A and MOAP-1 in cancers." (PMID 27294960, 2016). "Although the CpG island of MOAP-1 is 954 base pair long containing about 110 CpG sites within the promoter region (as obtained via MethPrimer), it does not appear to be regulated by promotor-specific methylation in cancers." (PMID 27294960, 2016). "Furthermore, overexpressed MOAP-1 in several cancer cell lines resulted in reduced formation of tumors in a xenograft model in athymic nude mice suggesting a universal role as a tumor suppressor protein." (PMID 26269600, 2015). "Given that RASSF1A expression is frequently lost during carcinogenesis and Bax is mutated in a large percentage of gastrointestinal and colorectal cancers, it is plausible that MOAP-1 expression and/or function may also be regulated during cancer development." (PMID 22745908, 2012). "The upregulation of MOAP-1 protein levels can also occur in response to chemical toxins and clinical drugs reaffirming our speculation that MOAP-1 in cancer cells may be important for patient response to certain chemotherapeutic treatments." (PMID 22745908, 2012). "Besides cancers and neuronal diseases, MOAP1 was also related to a few other diseases." (PMID 35269511, 2022). "UBR5-mediated degradation of MOAP-1 and MOIP-1 confers cisplatin resistance in ovarian cancer, illustrating the capacity for UBR5 to enhance cancer cell survival following chemotherapy." (PMID 39857943, 2025). "Re-introduction of MOAP1 induced the expression of apoptotic proteins BAX and cleaved caspase 3 in miR-92a-3p expressing CRC cells, thus promoting cancer cell apoptosis." (PMID 31064356, 2019). "Recently, we published that the pro-apoptotic protein, MOAP-1, and downstream effector of the RASSF1A pro-apoptotic pathway is a tumor suppressor protein whose expression varies widely in cancers." (PMID 27294960, 2016). "MOAP-1 can also promote intrinsic cell death, activation of BH3-containig proteins and is regulated in cancer by ubiquitin-dependent degradation." (PMID 27294960, 2016).
cancer (continued). "In summary, UBR5 interacts with key proteins such as MOAP-1, MOIP-1, β-catenin, TXNIP, MYC, CDC73, CAPZA1, TIP60, GKN1, and ECRG4, NF-kB, highlighting its pivotal roles in promoting metastasis, therapeutic resistance, and cancer cell survival." (PMID 39857943, 2025). "Additionally, exosomal miR-92a-3p derived from colorectal CAF targets anti-tumor F-box/WD repeat-containing protein 7 (FBXW7) and a modulator of apoptosis 1 (MOAP1), thereby endowing chemoresistance to cancer cells." (PMID 34760886, 2021). "Furthermore, the absence of MOAP-1 in cancer cells would also impact to some extent on the intrinsic apoptotic pathway(s) where MOAP-1 has been shown to play a role and which is also the target of many chemotherapeutic drugs." (PMID 22745908, 2012).
tumor (13 papers, 2012 to 2026). "In addition, the important role of RASSF1A in modulating tubulin stability may be shared with its association with MOAP-1 to further strengthen the role of the RASSF1A/MOAP-1 tumor suppressor pathway." (PMID 26269600, 2015). "Hu and colleagues discovered that miR-92a-3p in CAF-secreted exosomes targets FBXW7 and MOAP1 in tumor cells, enhancing β-catenin expression, tumor stemness, and EMT, while inhibiting apoptosis and leading to metastasis and chemoresistance in CRC." (PMID 39578849, 2024). "Together, the data suggest that the cytotoxicity of α-mangostin involves the activation of MOAP-1 tumor suppressor and its interaction with act-BAX, leading to mitochondria dysfunction and cell death." (PMID 35082905, 2022). "Since the in-vitro MOAP1 expression level is low in tumor cells, MOAP1 ubiquitin can be reduced by apoptosis stimulating processes." (PMID 35269511, 2022). "Not surprisingly, tumor formation was additionally reduced in the presence of HA-RASSF1A (for DAOY and H1299 cells) suggesting a requirement for the RASSF1A/MOAP-1 apoptotic pathway in inhibiting tumor formation in these cell lines." (PMID 26269600, 2015). "Our current data support the role of MOAP-1 as a tumor suppressor involved in cell death, tubulin stability, and in several unexplored biological functions important for its ability to mediate growth suppression." (PMID 26269600, 2015). "Complementary to our overexpressed cells, shRNA knockdown of MOAP-1 resulted in a significant increase in tumor formation following subcutaneous injection of HCT116 cells containing shRNA to MOAP-1." (PMID 26269600, 2015). "Interestingly, the loss of the function of the BH3 domain of MOAP-1 (either as a deletion or mutation) resulted in the inability to suppress tumor formation to suggest a significant dependence of MOAP-1 on its pro-apoptotic function to carry out tumor suppression." (PMID 26269600, 2015). "Likewise, TRIM39 E3 ligase inhibits APC/CCDH1‐mediated degradation of MOAP1 (Modulator of Apoptosis 1), a tumour suppressor that activates the pro‐apoptotic Bax protein." (PMID 36881608, 2023). "Additionally, Ras-association domain family 1 isoform A (RASSF1A) is a potential tumor suppressor correlated with the modulator of apoptosis 1 (MOAP-1), which promotes Bax conformational changes and its activation." (PMID 34298639, 2021). "Thus, association with tubulin is an important aspect of the tumor suppressor role for RASSF1A and possibly MOAP-1 due to the intimate connection between these two pro-apoptotic proteins." (PMID 26269600, 2015). "Mechanistically, we can demonstrate that MOAP-1 may carry out its tumor suppressor function by the involvement in apoptosis and associations with tubulin isoforms to stabilize tubulin (this study)." (PMID 26269600, 2015). "Although cell death and microtubule stability are important aspects of MOAP-1 biology, other possible mechanisms may exist to explain how MOAP-1 inhibits cell proliferation and tumor formation." (PMID 26269600, 2015). "Furthermore, in a classical xenograft assay, both RASSF1A and MOAP-1 can suppress tumor formation in HCT116 colon cancer cells suggesting tumor suppressor function and functional importance for both genes in growth inhibition in normal cells." (PMID 22745908, 2012). "MOAP-1 may possess a potential tumor suppressor function in specific cell types." (PMID 26269600, 2015). "Therefore, it will be interesting to explore which of these biological processes MOAP-1 may also be involved in and that may be important for it to behave as a potential tumor suppressor protein." (PMID 22745908, 2012). "This can inhibit mitochondrial apoptosis and activate the Wnt/β-catenin pathway by suppressing F-Box and WD repeat domain containing 7 (FBXW7) and modulator of apoptosis 1 (MOAP1), thus promoting the EMT and metastasis of tumor cells." (PMID 39139454, 2024). "Furthermore, loss of the BH3 domain of MOAP-1 resulted in lack of tumor suppressor function." (PMID 26269600, 2015).
tumor (continued). "Because most of the tumor growth initiates between 7 and 14 days, we postulate that >60% of the HCT116 cells expressing Myc-MOAP-1 will be sufficient to direct a growth path toward tumor suppression." (PMID 26269600, 2015). "Furthermore, we speculate that MOAP-1 may cooperate with RASSF1A to promote tumor suppression." (PMID 22745908, 2012). "Adding further evidence for its tumor suppressor function, our xenograft assays suggest that MOAP-1 can be additive to the tumor suppressor property of the RASSF1A and that the pro-apoptotic function of MOAP-1 may govern the tumor suppressor function." (PMID 26269600, 2015).
infection (11 papers, 2011 to 2025). The state of being infected such as from the introduction of a foreign agent such as serum, vaccine, antigenic substance or organism. "In Magnaporthe oryzae, several bZIP genes, including MoATF1, MoHAC1, MoAP1, MoBZIP10, and MoMETR, are essential for host infection." (PMID 40003918, 2025). "The bZIP TF MoAP1 (MobZIP21 in S4 Table) is required for infection and other cellular processes such as resistance to oxidative stress and development." (PMID 38252628, 2024). "Previous studies showed that some bZIP genes were required for host infection in M. oryzae, and they also exhibited increased expression levels in the infection stages, such as MoATF1, MoHAC1, MoAP1, MoBZIP10, and MoMETR." (PMID 35049973, 2021). "In the hemibiotrophic pathogen M. oryzae, Moap1 is essential to the growth of invasive hyphae for successful infection." (PMID 34630367, 2021). "In this study, we demonstrated that HIGS of M. oryzae transcription factor gene MoAP1 is efficient for controlling the infection of rice blast fungus." (PMID 31024598, 2019). "To understand how HIGS of MoAP1 leading to enhanced blast resistance, we examined the infection process of the GFP-tagged strain GZ8 by laser scanning confocal microscopy." (PMID 31024598, 2019). "MoAP1 is highly active during infection and is translocated from the cytoplasm to the nucleus in response to oxidative stress induced by H2O2." (PMID 29186370, 2017). "In contrast, the appressoria and infection hyphae of the wild type strain had less formazan precipitates than the Moap1 mutants." (PMID 21383978, 2011). "During infection, the fungus may be able to take up siRNAs from the plant cells, resulting in decreased MoAP1 gene expression via an RNAi mechanism." (PMID 31024598, 2019). "Then, we examined the expression of MoAP1 in the fungal mass collected at the infection area." (PMID 31024598, 2019). "Thus, we concluded that the MoAP1 was highly activated during conidiation and infection." (PMID 21383978, 2011). "To further explore the effect of FBXW7 and MOAP1 on metastasis and 5-FU/L-OHP resistance of CRC, we constructed SW620/Mock, SW620/miR-92a-3p, SW620/miR-92a-3p/FBXW7, SW620/miR-92a-3p/MOAP1 cells by lentivirus infection." (PMID 31064356, 2019). "When observation was made at 7 days post infection, there were still no typical lesions developed on Moap1 mutant infected leaves." (PMID 21383978, 2011). "Moreover, DAB staining showed the accumulation of ROS at the infection site of the Moap1 mutant, but not the wild type and complemented strains." (PMID 21383978, 2011). "However, Moap1 was not required for infection in the host plant." (PMID 27706212, 2016).
blood cancers (1 paper, 2015). "In contrast to the solid cancers, MOAP-1 in several blood cancer cell lines revealed two distinct forms as detected by two independent antibodies (right side)." (PMID 26269600, 2015). "We are currently investigating why MOAP-1 appears as a slower migrating band in blood cancers, but we suspect that it may involve phosphorylation of MOAP-1 by an unidentified kinase." (PMID 26269600, 2015).
heart disease (1 paper, 2022). "For example, MOAP1 was targeted by miR-25 to block the apoptosis of vascular smooth muscle cells, which plays a critical role in inflammation and heart disease." (PMID 35269511, 2022).
neurological diseases (1 paper, 2022). "MOAP1 is speculated to be associated with neurological diseases, and there are a few studies in this area." (PMID 35269511, 2022).
MOAP1 also shares sentences with these, for which no sentence is quoted: Abdominal obesity (1 paper); Anxiety (1); breast tumors (1); colon cancer (1); fibrocystic disease (1); glioblastoma (1); hereditary spastic paraplegia (1); Obesity (1).